MDM2 (MDM2 proto-oncogene)
Diseases named in the same sentence as MDM2 in open-access papers (continued):
Sharing a sentence is not in itself a finding about the gene and the disease.
cancer (continued). "This approach highlights how protein-protein interfaces can be exploited to develop novel Biologics, which can be used to dissect signal transduction mechanisms and provide leads for novel therapeutics to target specific MDM2 protein-protein interactions in cancer cells." (PMID 22916255, 2012). "MDM2 and p14ARF genotype frequencies of cancer-free controls and SGC cases." (PMID 23145162, 2012). "MDM2 is suggested to be a potential target for human cancer therapy." (PMID 22911819, 2012). "The MDM2 oncogene is amplified and overexpressed in various human cancers." (PMID 22911819, 2012). "This will decrease the efficacy for anti-Mdm2-based cancer therapy." (PMID 22410433, 2012). "The further optimisation of peptide 35 as an MDM2-targeting lead that co-ordinates NEDDylation might provide a novel pharmacological tool to test as an anti-cancer therapeutic." (PMID 22916255, 2012). "Interestingly HMGA2 is frequently coamplified with MDM2 in human malignant tumours, particularly WDLPS and DDLPS." (PMID 21253554, 2011). "The MDM2 gene is a cellular proto-oncogene amplified in 25%–40% of all human cancers." (PMID 23724261, 2011). "Cancer cells with MDM2 gene amplification are most sensitive to nutlin-3 in vitro and in vivo." (PMID 22016618, 2011). "Over the last decade, many groups including ours have extensively worked on developing small molecule inhibitors of MDM2 (here MI-219, developed in collaboration with Ascenta Therapeutics) and tested them against multiple cancers including lymphoma, PDAC, colon and breast." (PMID 21623005, 2011). "Due to recent findings of the MDM2 SNP309T>G polymorphism enhancing MDM2 transcription and its potential association to increased cancer risk, we hypothesized that the MDM2 SNP309G genotype may be associated with lack of response to an anthracycline regimen." (PMID 21556366, 2011). "The overexpression of MDM2 has been observed in many types of cancer." (PMID 21829536, 2011). "MDM2 overexpression is frequently detected in many human cancers, suggesting that MDM2 overexpression may be one of the common features of tumorigenesis." (PMID 22133303, 2011).
cancer (continued). "Despite its role as a proto-oncogene, so far, neither MDM2 germ line mutations nor increased gene copy number at the germ line level has been identified in cancer prone families." (PMID 21436469, 2011). "However, the apoptotic response in cancer cells with normal levels of MDM2 can vary dramatically, suggesting that other mechanisms or modifying factors are involved in the response to MDM2 antagonists." (PMID 21624110, 2011). "Although MDM2 SNP309 was not a significant cancer risk factor via the log-rank test or in univariable analysis, it was linked to a 1.58 times greater likelihood of developing cancer than TT homozygosity after adjusting for other confounders." (PMID 20520810, 2010). "The mdm2 oncogene is amplified and/or over expressed in several cancer types." (PMID 20591158, 2010). "In addition, as MDM2 SNP309 status has been demonstrated to affect the overall age of onset of various cancers, with differential effects in different populations, we have explored its effects in this unique population." (PMID 20219101, 2010). "There have been several reports of MDM2 amplification and/or overexpression in human cancers." (PMID 19707204, 2009). "However the MDM2 SNP309 G/G correlation with cancer onset age in their study seemed to be restricted to non mutant breast familial cancer cases and was not apparent in the BRCA1/2 mutation carriers." (PMID 19226467, 2009). "In the under 51 years old they found a much larger fraction of patients harboring MDM2 SNP309G/G compared to the fraction of patients harbouring this SNP in the over 51 years old, supporting a role for this SNP as a modifier of cancer risk in BRCA1/2 mutation carriers." (PMID 19226467, 2009). "A functional polymorphism within MDM2, SNP309 T>G, has been linked to early onset cancer." (PMID 18828900, 2008).
cancer (continued). "However, many questions need to be answered before we can understand the true utility of MDM2 antagonists in cancer therapy." (PMID 15452548, 2004). "However, researchers have demonstrated the potential of utilizing MDM2 in cancer treatment." (PMID 40191734, 2025). "However, multiple immunohistochemical studies have demonstrated clear differentiation between the lesion and the primary pathology, particularly through the detection of MDM2 and CDK4 rearrangements, as well as evidence of deubiquitination in cancer-associated pathways." (PMID 40926903, 2025). "In addition, data from the Cancer Therapeutics Response Portal (CTRP) database of the Broad Institute indicate that LTβR expression is negatively correlated with the efficacy of certain anti-cancer drugs, including doxorubicin (topoisomerase II inhibitor) and nutlin-3a (MDM2 inhibitor)." (PMID 40883295, 2025). "Therefore, targeting the lid in the screening and design of Mdm2/MdmX inhibitors may offer a novel strategy for developing anti-cancer drugs." (PMID 40427535, 2025). "This difference may reflect the distinct roles of MDM2 in acute inflammation versus cancer." (PMID 40371345, 2025). "Additionally, MDM2 mRNA levels were significantly elevated in cancer patients compared to controls." (PMID 39857959, 2025). "The pronounced gear-like nuclear atypia reported to be associated with MDM2 amplification in carcinoma ex PA4 might be a rare phenomenon and was not particularly recognizable in our cases." (PMID 40033554, 2025).
cancer (continued). "Therefore, identifying additional molecules that interact with MDM2 would be crucial for further understanding of its oncogenic activity and may result in the identification of new targets for cancer treatment." (PMID 38263255, 2024). "Intriguingly, the gene expression levels of BCL2, CDK2, MDM2, Casp9 and P21 were reversed in HeLa cells treated with L. cornuta ethyl acetate fraction when compared with the untreated HeLa cells, indicating its potential to regulate cell proliferation, apoptosis, and cell cycle in cancer cells." (PMID 39005932, 2024). "For malignant tumors, it is typical that cell cycle or proliferation is accelerated by oncogene mutation, and in LPS, this is associated with the high level of amplification of the chromosome 12q1315 region, including CDK4 and MDM2 (regarded as cell cycle oncogenes)." (PMID 39063036, 2024). "Thus, the MDM2-targeting PROTAC therapeutic approach may have better prospects for cancer treatment." (PMID 39748950, 2024). "Therefore, cancer-specific MDM2 inhibitors should be developed." (PMID 38811536, 2024). "Furthermore, results from the in silico GI screens identified several SL candidates—namely NDUFB5 (in the STAD screen), MDM2 and TUBA1B (in the COAD/READ screen), and WRN (in the pan-cancer and COAD/READ screens)—which encode proteins that can be inhibited using existing and in-development drugs." (PMID 39578878, 2024). "In other cancers, the anticancer mechanism of parthenolide is believed to be mainly related to the inhibition of NF-κB, and other mechanisms include the inhibition of mouse double minute 2 homolog (MDM2), HDAC1, transcription protein 3 (STAT3), and glutathione (GSH)." (PMID 39595109, 2024). "Further studies are required to elucidate the functional consequences of the interaction between RPS4X and MDM2 in cancer cells and may contribute to reinforcing the evidence that it could be a biomarker for these cancers, which may help in more effective treatment for patients." (PMID 39199272, 2024). "Therefore, sourcing natural products that can effectively inhibit the NOX2, NF-κβ, and mdm2 proteins may be a worthwhile strategy for the identification of ROS, inflammation, and cancer drug candidates, respectively." (PMID 39124928, 2024).
cancer (continued). "Consequently, MDM2 inhibitors have been extensively explored as anti-cancer therapies." (PMID 37454155, 2023). "In our study, we have confirmed that the MDM2 could promote cancer survival through HIF-1." (PMID 36741966, 2023). "Moreover, inhibition of MDM2 has also been shown to radiosensitize cancer cells." (PMID 37298284, 2023). "In the pan-cancer analysis, a decreased probability of overall survival (OS) and disease-specific survival (DSS) was found in amplified tumors in comparison with non-amplified ones, with EGFR, CDK4, MDM2, KRAS, and CCNE1-amplified tumors being those associated with a worse prognosis." (PMID 36980521, 2023). "Thus, Mdm2 inhibition is a two-edged sword for cancer patients." (PMID 37024504, 2023). "Therefore, the inhibitors of MDM2 are promising anti-cancer drugs." (PMID 35865631, 2022).